STAT3 (signal transducer and activator of transcription 3)
Diseases named in the same sentence as STAT3 in open-access papers (continued):
Sharing a sentence is not in itself a finding about the gene and the disease.
tumor (continued). "HNSCC tumor cells produce IL-6, CXCL8, and epidermal growth factor (EGF), which improve the survival and angiogenic potential of endothelial cells through the activation of the STAT3/protein kinase B (AKT)/extracellular signal-regulated kinase (ERK) signaling pathways." (PMID 38003931, 2023). "Furthermore, because our group and others have demonstrated the importance of the JAK2/STAT3 pathway in the regulation of IBC cellular identity, stemness, and tumor progression, herein, we also investigated the modulation of STAT3 expression after MTDH knockout." (PMID 36902125, 2023). "Therefore, IL-10 can regulate the TLR4/NF-κB pathway in dermal fibroblasts through the IL-10 receptor (IL-10R)/STAT3 axis to reduce both ECM protein deposition and fibroblast transformation to myofibroblasts, thereby inhibiting the formation of skin scar induced by lipopolysaccharide." (PMID 36873898, 2023). "Specifically, we experimentally determined whether Wnt/β-catenin and IL6-JAK-STAT3 signal pathways were activated in ccRCC by examining the expression of TTC13, β-catenin, JAK2, p-STAT3, STAT3 and p-JAK2 in ccRCC tumor tissues as well as the adjacent normal tissues." (PMID 37927783, 2023). "The transcription factor STAT3 is frequently activated in a variety of malignancies and emerging data points toward STAT3-mediated upregulation of OXPHOS as a mechanism of survival in drug-resistant tumours and a potential marker for drugs targeting mitochondrial metabolism." (PMID 36823364, 2023). "Basic leucine zipper ATF‐like transcription factor (BATF), involved in the synergistic induction of target gene expression, is further induced by co‐binding of STAT3 and STAT6, and high levels of BATF expressed from macrophages may contribute to tumor progression." (PMID 38098217, 2023). "High levels of activated ERK, AKT and STAT3 have been observed in seminomas and nonseminomatous germ cell tumors, and may participate in tumor proliferation and survival." (PMID 36614308, 2023). "Indeed, it has been reported that in the tumor microenvironment, IL-21 exerts a lot of biological activities, stimulating the Janus family tyrosine kinases (JAK), JAK1 and JAK3, as well as triggering STAT1, STAT3, and STAT5." (PMID 37759505, 2023). "However, is it possible that worm ESPs activates STAT3/PD-L1 pathway like tumor cells, bacteria, and other pathogens, which has not been reported yet?" (PMID 36238295, 2022). "While these stories are still unfolding, it is necessary to avoid a purely negative view of STAT3 and pay attention to chronology, sex, or other factors that may influence the role of STAT3 in tumor development and progression." (PMID 35406557, 2022). "Due to STAT3 and MAPK pathway crosstalk, inhibition of one pathway may lead to upregulation of the other; targeting both pathways simultaneously would likely exhibit a stronger inhibitory effect on tumours." (PMID 36084109, 2022). "We attempted investigation of combined Smo and STAT3 inhibitor treatment in vivo; however, due to the potency of Smo inhibitors alone in our murine model, resulting in tumor eradication for many months, the model is not adequate for investigating synergy or Smo inhibitor resistance in vivo." (PMID 34482626, 2022). "An important implication is that therapeutic blockade of a single cytokine or its receptor may not be sufficient to abrogate STAT3 signaling and acquired chemoresistance in tumor cells that are subjected to multiple cytokine stimuli that exist in the TME." (PMID 35159191, 2022).
tumor (continued). "Highly expressed p-STAT3 was positively correlated to high levels of IL-4, IL-6, and IL-10, and negatively correlated to low levels of IFN-γ in the serum, which may contribute to immune surveillance disability against tumor cells." (PMID 35530361, 2022). "Nevertheless, given that Slug is considered “undruggable” due to inherent biological properties, inhibition of STAT3 phosphorylation at Y705 can be exploited to antagonize ERKi treatment-induced Slug upregulation, thereby blocking ERK inactivation-induced EMT, CSC enrichment, and tumor relapse." (PMID 36276640, 2022). "In addition, myCAFs could also affect several signaling pathways related to tumor cell stemness, such as the STAT3, KRAS, and Notch signaling pathways, suggesting that the abundance of myCAFs may affect tumor stemness." (PMID 35309916, 2022). "By examining the anti-tumor potential of ANPs, we provided sufficient information that ANPs inhibit the conversion of GDP-RAS to GTP-RAS, the RAS-MEK1/2-ERK1/2 kinase cascade, and the RAS-MEK1/2-ERK1/2 kinase cascade cross-talk with VEGF, β-catenin, JNK, WNT, and STAT3." (PMID 36010974, 2022). "Infiltration of Th17 in tumor microenvironment has been shown to promote tumor growth and angiogenesis, through induction of angiogenic factors (vascular endothelial growth factor/VEGF and prostaglandin E2/PGE2) and activation of oncogenic IL-6/Stat3 signaling." (PMID 36544761, 2022). "Similarly, STAT3 activated the secretion of LCN2(lipocalin 2) from N2 neutrophils, which induced mesenchymal-epithelial transition of tumor cells via ERK/KLF4 signaling pathway and thereby facilitating colonization and metastatic outgrowth in lung under the circumstance of nicotine." (PMID 35356244, 2022). "However, a recent investigation on LSCC tissues from 63 patients revealed a significant inverse correlation between miR-155, which was overexpressed in tumor tissues compared to control mucosa and SOCS1 protein, which, in turn, inversely correlated with STAT3 protein expression in the same samples." (PMID 35406495, 2022). "For instance, global STAT3 targeting in the TME may be beneficial in the T cell compartment but harmful for B cells; ways to deliver treatments in a targeted manner will take advantage of the diversity within the TME to yield optimal anti-tumor responses." (PMID 35406557, 2022). "To assess the therapeutic potential and examine the role of STAT3 in SHC4-induced tumorigenesis, we performed another subcutaneous xenograft model, in which nude mice were peritoneally treated with Stattic for 4 weeks after subcutaneous tumor reached 3–5 mm in diameter." (PMID 35033067, 2022). "Inhibition of STAT3 suppressed VEGF expression, regardless of whether the VHL gene mutation eventually led to reduced tumor angiogenesis." (PMID 36230984, 2022). "Although IL-6R and IL-11R are expressed in specific cell types, gp130 is ubiquitously expressed allowing for the activation of intracellular STAT3 signaling in cells with limited or no IL-6R and IL-11R expression, via sIL-6R and sIL-11R by tumor infiltrating neutrophils, monocytes and T-cells." (PMID 35053592, 2022). "Interestingly, STAT3 and NRF2 can also interact with each other to regulate tumor progression." (PMID 36557902, 2022). "In addition, we also observed in our in vitro study that a STAT3 inhibitor increased CXCL9 expression in tumor cells, indicating the balance of p-STAT1/p-STAT3 was a determinant in regulating chemokine production in tumor cells." (PMID 35925680, 2022). "We found that both giving STAT3 inhibitor or SPP1‐knockdown could decrease the tumor volume and tumor weight compared to the negative control group, which was more obvious after radiation." (PMID 35593388, 2022).
tumor (continued). "Both apigenin and luteolin (from 10 to 50 μM) inhibited STAT1 and STAT3 phosphorylation and decreased expression of STAT-dependent programmed death-ligand 1 (PD-L1), a major factor responsible for the suppression of the adaptive anti-tumor immune response in NSCLC and melanoma cell lines." (PMID 36555392, 2022). "However, the expression of STAT3-target genes Il11 and Socs3 was similar among gp130F/F:Nlrp3-/- and gp130F/F tumor and matched non-tumor gastric tissues at 3 and 6 months of age." (PMID 35299732, 2022). "STAT3 phosphorylates into p-STAT3 under the action of Janus kinase (JAKS), enters the nucleus and binds to specific DNA sequences, regulates the transcription and expression of related target genes, promotes tumor cell proliferation and drug resistance, and inhibits tumor cell apoptosis." (PMID 35463085, 2022). "Its negative role can be attributed to STAT3 inhibition of CXCR3-driven tumor trafficking." (PMID 35270020, 2022). "Moreover, OSM, through the activation of the STAT3, MEK, and JAK pathways, induced the expression of glucose-regulated protein 78 (Grp78) in HepG2 and Huh7 cells, a factor involved in proliferation, cancer progression, and the survival of tumor cells." (PMID 36077744, 2022). "A higher Ki67 expression in tumor cells and a higher number of CD163+ macrophages in ABC patients as compared with GBC ones has been observed, together with a high density of CD3+ and CD8+ cells, which correlated with STAT3 expression and microvascular density." (PMID 35328127, 2022). "However, the gene expression of STAT3 transcriptional factor was not changed over the same time, which was expected due to its role in rapid tumor growth and inflammation-driven tumorigenesis." (PMID 36139458, 2022). "Notably, both control and tumor-treated SCs were able to alter gene expression in SCLC cells, although the effect of tumor-activated SCs on the expression of several genes, including STAT3, was significantly stronger than the effect of intact SCs." (PMID 36551618, 2022). "Inhibition of STAT3 or STAT5 signaling or genetic depletion of the fatty acid translocase CD36 inhibits the activation of oxidative metabolism and the induction of immunosuppressive function in tumor-infiltrating MDSC and results in a CD8+ T-cell-dependent delay in tumor growth." (PMID 35408873, 2022). "However, using TCGA databases, we found that the LMO4 & STAT3-signature did not have a prognostic value in 13 tumor types." (PMID 35805116, 2022). "Because STAT3 activation contributes to the GBM immunosuppressive microenvironment, this raises the possibility that STAT3, in cooperation with the heterogenous cell population of the tumor microenvironment, suppresses PRKAA/AMPKα to influence the metabolic cues that support tumor growth." (PMID 40396025, 2022). "Interestingly, several studies have shown that STAT3 is constitutively activated in invasive BCs, but not benign tumors, indicating that STAT3 is mainly involved in tumor progression and metastasis, rather than tumor initiation." (PMID 36299882, 2022). "Inhibition of the STAT3 or STAT5 signaling pathway or deletion of the fatty acid transpose CD36 gene inhibits the activation of oxidative metabolism and induction of immunosuppressive function in tumor infiltration MDSCs and leads to delays in tumor growth dependent on CD8+ T cells." (PMID 36106333, 2022). "Hallmark pathways involved in immune response were also very highly enriched in tumor epithelium compared with normal, including interferon-α and interferon-γ response, interleukin-6 (IL-6)/Janus kinase (JAK)/signal transducer and activator of transcription 3 (STAT3) signaling, and NF-κB signaling." (PMID 35394843, 2022). "Furthermore, the low expression of MIR4435-2HG in MKN45 cell-derived exosomes inhibited the Jagged1/Notch and JAK1/STAT3 pathways in macrophages; MIR4435-2HG downregulated exosomes were found to significantly inhibit GC tumor growth in vivo by establishing a mouse model." (PMID 36483041, 2022).
tumor (continued). "Furthermore, prior work from our group has revealed that CAF-derived IL-6 engages in tumor-permissive crosstalk by activating STAT3 signaling within tumor cells, and that heightened CAF-tumor cell IL-6/STAT-3 signaling crosstalk is a central mediator of chemoresistance in PDAC." (PMID 36107485, 2022). "In conclusion, combination treatment with anti-CTLA-4 mAb and MUC1 mRNA nanovaccine could increase the infiltration of CD8+ T cells into tumor sites and enhance anti-tumor cytotoxic T-lymphocyte activity by reducing immunosuppressive TME and inhibiting tumor-promoting STAT3 signaling pathway." (PMID 34875483, 2022). "Likewise, tetraarsenic hexoxide (As4O6) could inhibit the phosphorylation of mitochondrial STAT3 and activate mitochondrial ROS-mediated GSDME pathway, to induce pyroptotic cell death in TNBC cells, and finally inhibit tumor growth and metastasis of TNBC." (PMID 35414025, 2022). "Therefore, we hypothesized that IGFBP2 increases the expression of IDO by activating STAT3 signaling in PDAC, thereby inducing Treg differentiation and promoting tumor progression." (PMID 36556226, 2022). "Represented by IL-1 and IL-6, primary mediators of GBM tumor cells in the inflammatory TME can orchestrate immunological activation and inflammatory signaling cascades such as hypoxia-inducible factor-1α (HIF-1α), Wnt-1, nuclear factor-kappa B (NF-κB), and STAT3 in GBM." (PMID 35572545, 2022). "Moreover, we showed that BLCAP interacted with STAT3 and reduced STAT3 phosphorylation, overexpressed PRADX activated STAT3 phosphorylation, and promoted ACSL1 expression via suppressing BLCAP expression, accelerating tumor metabolism." (PMID 35574370, 2022). "In summary, we highlight the profound effect of pY-Gel supramolecular hydrogel on skin damage repair and demonstrate that GMSCs-CM may promote skin cell proliferation and migration through activation of the EGFR/STAT3 signaling pathway, which ultimately promotes skin injury repair." (PMID 36231051, 2022). "Moreover, the relevance of ROBO3-dependent STAT3 activation in BL subtype identity and plasticity was supported by decreased expression of the p-STAT3 downstream target WNT10A, a member of the canonical WNT pathway and driver of EMT-related tumor cell invasion." (PMID 35993361, 2022). "Solid Tumors: Although CuQ (0.5–1 mg/kg) inhibited tumor growth most effectively using A549 cells in a mouse xenograft model along with reduced p-STAT3 levels in a series of cancer cell lines, CuQ (10 μM) did not elicit a change in p-JAK2 (with contrasts with responses to CuA, CuB, CuE, and CuI)." (PMID 36355554, 2022). "Interestingly, it was shown that the tumor-derived cytokines are able to activate the p38 MAPK pathway and STAT3 signaling in DCs, leading to lower expression levels of costimulatory molecules (i.e., CD40, CD80), activation markers (e.g., HLA-DR) and CD1a, and functionally abnormal DCs." (PMID 35965494, 2022). "Twenty-four hours after administration, APG-2449 exerted dose-dependent suppression of tumor phosphorylated ALK (p-ALK), Ak strain transforming (p-AKT), extracellular signal-regulated kinase (p-ERK1/2), and signal transducer and activator of transcription (p-STAT3)." (PMID 35820889, 2022). "MAFF could promote tumor invasion and metastasis through IL11 and STAT3 signaling." (PMID 36275774, 2022). "However, the consequence of STAT3 activation in type I collagen-expressing fibroblasts for the tumor growth of CRC in vivo has not been addressed yet." (PMID 35326623, 2022). "Furthermore, anti-ALK drugs such as crizotinib, alectinib, and ceritinib may downregulate the STAT3 pathway in pcALCL patients with ALK rearrangements, resulting in tumor cell death." (PMID 35406421, 2022).
tumor (continued). "Other terpenoids, such as Ginkgolide C (GGC) and eupatolide isolated from Ginkgo biloba (Ginkgoaceae) leaf and Inula helenium, respectively, could effectively attenuate the phosphorylation of STAT3 and its upstream kinases, demonstrating significant inhibition of NSCLC tumor growth." (PMID 36559280, 2022). "Given the potential role of IL6ST/STAT3 axis in SMG1 regulation and the important role it might play in tumor antigenicity we interrogated the RNA expression data from TCGA repository so as to identify immune pathways that could be associated with the expression of SMG1." (PMID 36443756, 2022). "Tumor‐derived legumain interacts with endothelial integrin αvβ3 through its Arg‐Gly‐Asp (RGD) motif and indirectly downregulates the expression of zonula occludens 1 via the STAT3 signaling pathway, which can promote tumor metastasis by increasing the permeability of endothelial barriers." (PMID 35067006, 2022). "Moreover, inhibition of STAT3 decreased splenic MDSCs, but no significant change in MDSCs was found in the tumor site." (PMID 36163047, 2022). "However, inflammatory cells produce tumor necrosis factor-α, transforming growth factor-β, interleukin-6 (IL-6), and other cytokines, which regulate the transcription factor NF-κB and the signal transducer and activator of transcription-3 (STAT3) pathways, and promote tumor cell metastasis." (PMID 36686786, 2022). "To evaluate a potential clinical applicability of our findings, we tested whether inhibition of the gp130/STAT3 signal axis with already established compounds impacts on CRT resistance and whether it can suppress the growth of tumor transplants under CRT in a living organism." (PMID 33530306, 2021). "Similarly, we found that PS-acet.-STAT3 peptide, but not PS-STAT3-KR or PS-unacet.-STAT3 peptide, was effectively accumulated in tumor cells and in tumors in which acetyl-STAT3 level was elevated." (PMID 33491667, 2021). "Moreover, alpelisib inhibited the expression of p-STAT3(Tyr705) and YAP in tumor lesions." (PMID 34625531, 2021). "The administration of the anti-IL-17 antibody significantly reduced pSTAT3 expression in STAT1-/- animals, suggesting that IL-17 may promote tumor growth in the absence of STAT1 through the activation of the STAT3 signaling pathway." (PMID 34299314, 2021). "First, STAT3 is often overactivated in HNSCC and induces the secretion of immunosuppressive cytokines, thereby promoting recruitment of immune suppressive regulatory T cells and myeloid-derived suppressor cells to the tumor microenvironment (TME) while hampering the development of dendritic cells." (PMID 35047999, 2021). "Recently, a potent STAT3 degrader SD-36 based on the proteolysis targeting chimera (PROTAC) concept, utilizing a ligand for cereblon/cullin 4A E3 ligase and a peptidomimetic STAT3 SH2 domain inhibitor, was discovered and showed potent anti-tumor activities in blood cancer." (PMID 33391507, 2021). "This may explain why the constitutive activation of STAT3/p-STAT3 is common in tumour cells but is not often seen in normal cells." (PMID 34789292, 2021). "Moreover, our group has previously identified other STAT3 and STAT5 blockers namely formononetin and ophiopogonin D, which can exert significant anti-tumor effects through increased ROS production in different tumor models." (PMID 33807326, 2021). "Another study showed that Palbociclib treatment led to the downregulation of the DNA repair pathway and the upregulation of IL-6/STAT3 pathway, and the combination using STAT3, PARP andCDK4/6 inhibitors could target these pathways and greatly inhibit tumour growth." (PMID 33832512, 2021). "In sum, analysing different MB cell lines, primary tumour samples, orthotopic xenograft models, and an immunocompetent MBGroup3 mouse model, we demonstrate a novel mechanism of action for AMBRA1 in the control of MBGroup3 oncogenesis through regulation of both STAT3 signalling and autophagy." (PMID 34302498, 2021).